H19 (H19 imprinted maternally expressed transcript)
Diseases named in the same sentence as H19 in open-access papers (continued):
Sharing a sentence is not in itself a finding about the gene and the disease.
lung carcinoma (continued). "In contrast, overexpression or loss of imprinting (LOI) of H19 has been observed in a wide variety of tumors, including bladder carcinoma, epithelial ovarian cancer, esophageal cancer, lung cancer, breast adenocarcinoma, endometrial cancer, and invasive cervical carcinoma." (PMID 23711233, 2013). "In more detail, the uptake of H19 packaged in exosomes by lung cancer cells could result in the upregulation of H19 expression in these recipient cells and thereby cause cancer cell resistance to gefitinib, but H19 knockdown could contribute to the recovery of gefitinib sensitivity." (PMID 31728212, 2019). "H19 exerts its unfavorable effect on lung cancer cells through stimulating transcription of ZEB1 and 2, the target genes of the miR-200a." (PMID 39912974, 2025). "Conversely, increasing the expression of lncRNA H19 in sensitive lung cancer cell lines yields opposite effects." (PMID 38794196, 2024). "LncRNA H19 (H19), one of the members of lncRNA, is overexpressed in various tumors including breast, colorectal, and lung cancer." (PMID 39184399, 2024). "In lung cancer, H19 promotes tumor growth, angiogenesis, and metastasis through its interactions with miRNAs, transcription factors, and signaling pathways involved in tumor progression." (PMID 39201688, 2024). "Their research showed that ferroptosis was the mechanism by which curcumenol induced lung cancer cell death, and that the lncRNA H19/miR-19b-3p/FTH1 axis was crucial for this process." (PMID 38338400, 2024). "RNA sequencing revealed that treatment with curcumenol significantly downregulated the long non-coding RNA H19 (lncRNA H19) in lung cancer cells." (PMID 39104501, 2024). "Our study provides valuable findings on the intricate mechanisms by which β-elemene affects the sensitivity of lung cancer cells to gefitinib, highlighting the significant role played by lncRNA H19 and autophagy in this specific context." (PMID 38794196, 2024). "These insights collectively demonstrate β-elemene’s role in thwarting late-stage autophagy and highlight lncRNA H19 as a pivotal target for reversing gefitinib resistance in lung cancer, with its inhibition potentiating the therapeutic efficacy of β-elemene." (PMID 38794196, 2024). "Similar to many other cancer types, lncRNA H19 is upregulated in lung cancer cells and functions as a ceRNA that binds with miR-19b-3p to sponge RNA." (PMID 38355574, 2024). "In summary, our study demonstrates that β-elemene effectively overcomes lung cancer resistance to gefitinib by targeting lncRNA H19 and autophagy, thereby enhancing the efficacy of gefitinib." (PMID 38794196, 2024). "Our earlier research had demonstrated that curcumenol, the bioactive compound derived from Curcuma aromatic Salisb., exerts its ferroptosis-inducing effects in lung cancer cells through the inhibition of lncRNA H19." (PMID 38794196, 2024). "Our findings hint at a connection between lncRNA H19 and autophagy in resistant lung cancer cells, pointing towards an intricate regulatory network that awaits further elucidation." (PMID 38794196, 2024). "Through inhibiting HDAC2 binding to the H19 promoter, intratumoural Roseburia‐derived butyrate increases H3K27 acetylation and subsequently enhancing H19 expression, which promotes lung cancer cell progression." (PMID 39568157, 2024). "The extensive investigation conducted in this study aimed to assess the impact of β-elemene on the expression of lncRNA H19, autophagic mechanisms, and its potential role in overcoming gefitinib resistance in lung cancer cells." (PMID 38794196, 2024).
lung carcinoma (continued). "It has been shown that in lung cancer, higher expression of H19 is positively correlated with poor prognosis, and its knockdown significantly reduces tumor cell proliferation, suggesting that H19 plays a pivotal role in NSCLC progression." (PMID 37175885, 2023). "In lung cancer, H19 expression distinctly demonstrates a marked upregulation compared with adjacent normal tissues." (PMID 37901797, 2023). "Many such disorders have reported the involvement of H19, among which lung cancer makes frequent appearances in the medical literature." (PMID 36188624, 2022). "Some lncRNAs, such as H19, are detected and elevated in the circulation blood of lung cancer patients." (PMID 34976181, 2022). "H19 silencing suppresses ionizing radiation-induced DNA damage of lung cancer cells, but enhances DNA repair." (PMID 36230902, 2022). "H19 expression is significantly higher in lung cancer tissues than in adjacent normal tissues, and interestingly, H19 is elevated in the plasma of lung cancer patients." (PMID 34976181, 2022). "Given that H19 plays an important regulatory role in lung diseases such as lung cancer, pulmonary fibrosis, and pneumonia, targeting H19 is a promising area of research." (PMID 36188624, 2022). "Curcumin can significantly down regulate the expression of long-chain non coding RNA H19 (lncRNA H19) in lung cancer cells." (PMID 36408273, 2022). "Studies have shown that H19 is highly expressed in lung cancer tissues and cell lines, promotes lung cancer cell growth, migration, and invasion, and upregulates the expression of ZEB1 and ZEB2 to further promote EMT." (PMID 36686745, 2022). "Withdrawn: ‘The LncRNA H19/microRNA‐29b‐3p/HMGB1 signaling axis contributes to the regulation of lung cancer cell growth’, Xiaojun Zhong, Congkai Zhang, Yunlian Diao, Shu Liao, Qingyuan Ling, Zhuoxian Zhang,Jiuhong Zhong, Ping Long." (PMID 33527767, 2022). "Silencing of H19 has been reported to prevent cell proliferation and migration in lung cancer by reducing methylation of E‐cadherin promoter." (PMID 35166018, 2022). "Other studies, including our study, have disclosed that H19 is up-regulated in numerous human malignancies, such as intestinal, esophageal, bladder, breast, gastric and lung cancer." (PMID 36139647, 2022). "Elevated H19 expression has also been detected in lung cancer and its overexpression has been observed in smokers compared to never-smokers." (PMID 33684161, 2021). "Numerous previous studies have confirmed that the lncRNA H19 is highly expressed in samples of lung cancer." (PMID 34863180, 2021). "Recently, several researcher groups have shown that H19 promotes lung cancer progression through lncRNA-miRNA-mRNA network." (PMID 34421359, 2021). "LncRNAs are overexpressed in a variety of cancers, including lncRNA DGCR5 and DANCR in lung cancer, lncRNA H19 in melanoma, and lncRNA TUG1 in ovarian cancer." (PMID 34131102, 2021). "For the field of lung cancers, the high level of LncRNA H19 expression would lead to gefitinib resistance in non-small cell lung cancer, and the presence of LncRNA H19 are associated with the proliferation of lung cancer cells." (PMID 33799753, 2021). "Until now, only a limited number of CS-associated lncRNAs have been reported in lung cancer, namely, Smoke and Cancer-associated LncRNA–1 (SCAL1), HOX Transcript Antisense RNA (HOTAIR), H19, and Metastasis-Associated Lung Adenocarcinoma Transcript 1 (MALAT1)." (PMID 33684161, 2021). "The previous review article showed that the LncRNA H19 SNP rs217727 was significantly higher in the oral squamous cell carcinoma and lung cancer." (PMID 33799753, 2021). "For the lung cancers, the LncRNA H19 SNP rs217727 would lead to higher incidence of lung squamous cell carcinoma and LADC." (PMID 33799753, 2021).
lung carcinoma (continued). "At present, research on 1ncRNAs in cisplatin resistance in lung cancer was still in its infancy, and some lncRNA molecules related to cisplatin resistance in lung cancer had been screened and identified, including H19, XIST, SFTA1P, CCAT1, and MALAT1." (PMID 32626737, 2020). "A recent report has found that H19 was up‐regulated in A549 and H1299 lung cancer cells compared with normal lung BEAS‐2B cells and promoted NSCLC progression through STAT3 signalling way." (PMID 32281297, 2020). "The interaction between lncRNA H19 and miR-200a (a tumor-suppressive miRNA downregulated in patients with a high lung cancer stage) regulates the expressions of ZEB1 and ZEB2." (PMID 33412752, 2020). "First, we investigated the expressions of H19 and miR‐21 following different treatments in lung cancer." (PMID 32281297, 2020). "From a clinical point of view, plasma levels of H19 have been highlighted as predictive markers for breast, stomach, and lung cancers, but also as a way to follow the evolution of cancers." (PMID 33291403, 2020). "For example, the gene H19 (cg21926276 locate) is related with both lung cancer and tumor growth, methylation of which has been thought as a sensitive marker of tobacco history." (PMID 32302299, 2020). "Gong et al13 found that SNPs in HOTTIP, H19, and CCAT2 were associated with lung cancer risk, and SNPs in MALAT1, H19, CCAT2, HOTAIR, and ANRIL were related to lung cancer patients’ response to platinum‐based chemotherapy." (PMID 30980423, 2019). "In lung cancer, only a small part of lncRNAs, such as H19, HOTAIR, MALAT1, ANRIL, and GAS5 have been identified to be tumor-associated especially in lung cancers." (PMID 30154938, 2018). "In this study, we genotyped four tag SNPs of H19 gene (rs217727, rs2107425, rs2735469, and rs17658052) in a case-control study of lung cancer in northeast China." (PMID 30219045, 2018). "Thereby, the up-regulation of airway epithelial H19 expression can be considered as an early marker of epithelial cell development into lung cancer." (PMID 30219045, 2018). "A case-control study was performed, and H19 SNP rs217727 was analyzed in 555 lung cancer patients from two hospitals and 618 healthy controls to test the association between this SNP and the susceptibility to LC." (PMID 30071841, 2018). "H19 acts as a gene that is up-regulated in hypoxic stress and certain tumors, including lung cancer, and is therefore an indispensable regulator of tumor development." (PMID 30219045, 2018). "The oncogenic-like activity of this lncRNA is also supported by the decrease of the tumorigenic phenotype observed for a panel of breast and lung cancer cell lines upon H19 knock down." (PMID 29443889, 2018). "Recent reports had showed that many of the lncRNAs, including H19, HOTAIR, MALAT1, ANRIL, GAS5, and GAS5-AS1, were tumor-associated, especially in lung cancers." (PMID 30154938, 2018). "By down-regulating H19, an lncRNA confirmed more than 20 years ago, the breast and lung cancer cell clonogenicity and anchorage-independent growth can be significantly decreased." (PMID 28947982, 2017). "A reduction in clonogenicity and anchorage independent growth is observed upon depletion of H19 in both breast and lung cancer cells." (PMID 27129154, 2016). "We recently presented new evidence showing that the tumorigenic and scattering effect of HGF/SF on lung cancer cell lines which express MET receptor can be attenuated by H19 knockdown." (PMID 26623562, 2016). "This total ablation of E-cadherin was also shown in HCC and lung carcinoma cells overexpressing H19, together with the upregulation of the mesenchymal N-cadherin." (PMID 26536864, 2015).
lung carcinoma (continued). "The development of DNA-based therapy involving H19/miR-675 is underway in our lab, and show promising results in preclinical models of lung cancer." (PMID 25884481, 2015). "Most importantly, we provided strong evidence showing that the tumorigenic and scattering effect of HGF/SF on the A549 lung carcinoma cells can be attenuated by H19 knockdown." (PMID 25884481, 2015). "In an experimental mouse model of lung carcinoma metastasis that was induced by intravenous injection of cells, cells overexpressing H19 manifested improved ability to metastasize in comparison to control cells transfected with empty vector." (PMID 26536864, 2015). "In an attempt to understand the oncogenic role of H19 lncRNA in lung cancer, we utilized siRNA-mediated knockdown of H19." (PMID 25884481, 2015). "Over-expression of H19 in lung cancer lines abolished the expression of E-cadherin by activation of Slug in a miR-675 dependent manner, suggesting a biological function of H19 in the regulation of EMT." (PMID 26932376, 2014). "H19 knockdown significantly decreased the clonogenicity and anchorage-independent growth property of several breast and lung cancer cell lines." (PMID 23711233, 2013). "Clinically, we found that higher levels of mdig and H19 expression correlate with poorer survival of the lung cancer patients." (PMID 23965803, 2013). "H19 was found highly expressed in stomach and liver cancer cell lines, while lowly expressed in lung cancer and prostate cancer cell lines." (PMID 24063685, 2013). "Like miR-17-92, expression of the non-coding RNA H19 has been shown to be induced by MYC in lung carcinomas." (PMID 22852089, 2012). "It has been previously shown that the non-coding H19 mRNA is highly expressed, indicating active H19 promoter, in lung cancer cell lines, especially in A549." (PMID 21687669, 2011). "Downregulation of H19 RNA significantly decreased breast and lung cancer cell clonogenicity and anchorage-independent growth." (PMID 17786216, 2007). "In lung cancer, H19 represses miR-200a, resulting in increased expression of ZEB1 and ZEB2." (PMID 41516132, 2025). "H19: H19 is a maternally expressed lncRNA involved in embryonic development and genomic imprinting, whose dysregulated expression has been implicated in COPD and lung cancer progression." (PMID 39201688, 2024). "Thus, H19 inhibits ferroptosis in lung cancer cells via the H19/miR-19b-3p/FTH1 axis, thereby regulating cancer development." (PMID 38355574, 2024). "Among them, the lncRNA H19 is involved in developing multiple tumors, including lung cancer." (PMID 37175885, 2023). "Moreover, elevated H19 expression in lung cancer patients correlates significantly with advanced TNM stages, diminished disease‐free survival (DFS), and an unfavorable prognosis." (PMID 37901797, 2023). "lncRNA H19 can act as a competitive endogenous RNA to bind to miR-19b-3p, thereby enhancing the transcriptional activity of its endogenous target ferritin heavy chain 1(FTH1), and CUL plays a role in promoting ferroptosis by down-regulating lncRNA H19 in lung cancer cells." (PMID 37005430, 2023). "H19 silencing enhances the ferroptosis of lung cancer cells." (PMID 36230902, 2022). "In another research, GST-π expression is reported to be positively correlated with the resistance to cisplatin in lung cancer cell lines, which means H19 may affect the lung cancer drug resistance through H19/ GST-π pathway." (PMID 36246634, 2022). "Targeting H19 in lung cancer may represent a novel strategy for the diagnosis and management of this malignancy." (PMID 34976181, 2022). "Therefore, curcumin blocks the progression of lung cancer by inhibiting the lncRNA H19/miR-19b-3p/FTH1 axis to promote the ferroptosis process." (PMID 36408273, 2022). "In summary, H19 promotes the progression of lung cancer through multiple mechanisms and may also serve as a serological biomarker." (PMID 34976181, 2022).
lung carcinoma (continued). "Another study showed that Curcumenol could effectively inhibit the expression of H19 and promote the occurrence of ferroptosis in lung cancer." (PMID 36188624, 2022). "Except the EGFR, the long non-coding RNA H19 causes the progression and metastasis of lung cancer, and the LAMC1 SNP rs3768617 could also increase the risk of lung cancer." (PMID 36011604, 2022). "The correlation between H19 over-expression and lung cancer was reported in our previous studies." (PMID 36139647, 2022). "LncRNA H19 is involved in the development of almost all human cancers, including lung cancer." (PMID 33931980, 2021). "Therefore, more experiments in vivo and in vitro, as well as more clinical data, are needed to explore the exact role played by H19 regulating sensitivity to the various EGFR‐TKIs used in clinical treatment of lung cancer." (PMID 33931980, 2021). "Since the LncRNA H19 SNP rs217727 was related to lung cancer development and LncRNA H19 SNP rs2107425 was correlated to shorter metastasis-free survival, it may be reasonable for the similar condition in the current study." (PMID 33799753, 2021). "Since 2015, many scientists have focused their attention on the role of H19 in lung cancer." (PMID 34421359, 2021). "H19 increases gefitinib resistance via packaging into exosomes in non‐small cell lung cancer." (PMID 34130625, 2021). "Moreover, from this list, only H19, MALAT1, HOTAIR, and GAS5 were associated with exosomes and lung cancers in our PubMed search." (PMID 32438606, 2020). "Although many related miRNAs and signalling pathways are explored in H19‐regulated lung cancer cells, the combination effects between H19 and chemotherapeutic drugs in controlling progression of lung cancer and their tentative mechanisms are urgently needed to solve." (PMID 32281297, 2020). "Gong et al30 did not obtain any significant association between H19 gene rs2839698 polymorphism and lung cancer susceptibility, but suggested this SNP was associated with a platinum‐based chemotherapy response in lung cancer." (PMID 32207861, 2020). "Besides, both H19 and HOTAIR were identified as non-invasive diagnostic biomarkers in the sputum of lung cancer patients." (PMID 32438606, 2020). "LIN28 expression allowed by H19 leads to the promotion of lung cancer cell proliferation." (PMID 33291403, 2020). "The reduced H3K9me3 at the H19 promoter region promotes H19 expression in lung cancer cells." (PMID 33193379, 2020). "Since adenocarcinoma is one of the most frequent subtype of lung cancer, with a higher incidence in women, we analyzed the combined effects of the SNPs in H19 gene and cooking oil fume exposure on lung adenocarcinoma susceptibility among female never smokers in Shenyang, China." (PMID 30219045, 2018). "Recently, studies have suggested that H19 may participate in lung cancer (LC) development and progression." (PMID 30071841, 2018). "The polymorphism rs2107425 in H19 gene was associated with the risk of lung cancer among female who never smokes in Shenyang, China." (PMID 30219045, 2018). "The polymorphism rs2107425 in H19 gene is associated with the risk of lung cancer among female never smokers in Shenyang, China." (PMID 30219045, 2018). "Herein, in order to obtain the insight into the molecular mechanisms of H19 in cisplatin resistance in NSCLC, we made a comparison between cisplatin-resistant and cisplatin-sensitive human lung cancer cells by qRT-PCR and found that H19 is upregulated in cisplatin-resistant cells." (PMID 27911863, 2017). "Interestingly, in the same study, a similar mode of action for H19 was shown in vivo in mice where H19 overexpression increased the metastatic behavior of lung carcinoma cells." (PMID 26992233, 2016). "Based on a knockdown approach, down-regulation of H19 could significantly decrease the clonogenicity and anchorage-independent growth of breast and lung cancer cell." (PMID 27517318, 2016).